CNTNAP4 (contactin associated protein family member 4)
Description:
Presynaptic protein involved in both dopaminergic synaptic transmission and GABAergic system, thereby participating in the structural maturation of inhibitory interneuron synapses. Involved in the dopaminergic synaptic transmission by attenuating dopamine release through a presynaptic mechanism. Also participates in the GABAergic system (By similarity).
Synonyms: CASPR4; KIAA1763
Tractability: Antibody: UniProt places it where antibodies can reach, with medium confidence; UniProt predicts a signal peptide or a membrane-spanning region; its Gene Ontology location is reachable by antibodies, with medium confidence. PROTAC: its protein half-life has been measured.
Gene: Protein-coding gene on chromosome 16 (76,277,278 to 76,560,757, forward strand). Ensembl gene ENSG00000152910.
Subcellular location: Presynaptic cell membrane
Gene Ontology:
Molecular function: protein binding; PDZ domain binding
Biological process: nervous system development; regulation of grooming behavior; regulation of synaptic transmission, dopaminergic; regulation of synaptic transmission, GABAergic; signal transduction; modulation of chemical synaptic transmission; regulation of synapse organization
Cellular component: plasma membrane; presynaptic membrane; synapse; dendrite; GABA-ergic synapse
Genetic constraint (gnomAD): Loss-of-function variants: 73 observed, 106.77 expected, observed/expected ratio (o/e) 0.68, 90% interval 0.56 to 0.83. The synonymous counts are far from expectation, so gnomAD's model fits this gene poorly and the ratio says little. Missense variants: 1,594 observed, 1,330.9 expected, observed/expected ratio (o/e) 1.2, 90% interval 1.15 to 1.25. Synonymous variants: 611 observed, 488.14 expected, observed/expected ratio (o/e) 1.25, 90% interval 1.17 to 1.34.
Homologues: Orthologues: chimpanzee CNTNAP4 (99% identical), macaque CNTNAP4 (97% identical), dog CNTNAP4 (90% identical), pig CNTNAP4 (89% identical), mouse Cntnap4 (86% identical), guinea pig CNTNAP4 (86% identical), rabbit CNTNAP4 (86% identical), rat Cntnap4 (85% identical). Paralogues in human: CNTNAP3 (69% identical), CNTNAP3B (69% identical), CNTNAP5 (58% identical), CNTNAP2 (48% identical), CNTNAP1 (38% identical), CNTNAP3C (27% identical), NRXN2 (25% identical), NRXN3 (23% identical), NRXN1 (23% identical), CUBN (16% identical), HEPH (14% identical), HEPHL1 (14% identical), and 23 more.